KIFC1 (kinesin family member C1)
Diseases named in the same sentence as KIFC1 in open-access papers (continued):
Sharing a sentence is not in itself a finding about the gene and the disease.
cancer (continued). "KIFC1, a nonessential minus end-directed motor of the kinesin-14 family, is a centrosome clustering molecule, essential for viability of extra centrosome-bearing cancer cells." (PMID 26992853, 2016). "Additionally, KIFC1 interacts with key mitotic regulators, such as cyclins (Cyclin B1, Cyclin D, and Cyclin A), spindle assembly checkpoint proteins (MAD1-MAD2), and Aurora B kinase, ensuring successful mitotic progression and promoting uncontrolled proliferation in cancer cells." (PMID 40471955, 2025). "Out of 34 genes under such enhancer-like regulatory effect, only two (KIFC1 and HN1L) were over-expressed in cancer, both with significant negative correlation with DNA methylation." (PMID 40724805, 2025). "Ideal targets are kinesins whose expression is largely restricted to cancer cells and/or whose function is dispensable in non-malignant cells, as has been described for KIF20A, KIFC1, and KIF18A." (PMID 40002279, 2025). "Inhibitors against KIFC1 (e.g. AZ82) have been shown to be effective in vitro; however, their preclinical testing in cancer models is lacking." (PMID 36864125, 2023). "KIFC1, a nonessential kinesin motor protein, also known as HSET, plays a critical role in clustering of extra centrosomes in cancer cells." (PMID 26992853, 2016). "More importantly, this quantitative approach identifies genes potentially involved in cancer that have not been previously identified, such as KLHL21, KIFC1, and XAB2." (PMID 20454660, 2010). "Furthermore, we found that, like KIFC1, OTUD6B is a cancer-specific dependency, as its depletion reduced cell viability and colony formation in two TNBC cancer cell lines with centrosome amplification, but not in cells derived from normal breast." (PMID 39789388, 2025). "Similar to the KIFC1 inhibitor results, when cyclin/CDK inhibitor administration is delayed, it still proves to be highly effective at reducing PACC and 2N+ population sizes, but due to the existing resistance levels and population size, is not able to drive the cancer to extinction." (PMID 35962062, 2022).
tumor (56 papers, 2007 to 2026). "The correlation between KIFC1 expression and prognosis, tumor mutation burden, tumor purity, mismatch repair, and high-frequency tumor mutated genes was analyzed using a series of bioinformatic tools." (PMID 40612867, 2025). "Previous research has shown that KIFC1 is linked to the development and progression of several types of tumours, including prostate carcinoma, breast carcinoma, gastric carcinoma, endometrial carcinoma and non‐small cell lung carcinoma." (PMID 40857057, 2025). "Correlation analysis revealed a significantly positive association between increased KIFC1 expression and higher tumor grade (p < 0.05)." (PMID 39387242, 2024). "Significant positive correlation was observed between the mRNA expression of KIFC1 and the tumor mutational burden (TMB)." (PMID 37789080, 2023). "Bioinformatics analysis revealed a highly significant positive correlation between KIFC1 overexpression and signaling pathways associated with tumor proliferation pathways." (PMID 37955677, 2023). "High KIFC1 expression was found to be associated with high Gleason score, high tumor stage, metastatic lesions, high ploidy levels, and lower recurrence-free survival." (PMID 33760984, 2021). "Here we report that KIFC1, a centrosome clustering regulator, is positively associated with tumor recurrence." (PMID 33397932, 2021). "Specifically, the expression of KIFC1 was notably associated with tumor purity (r = 0.215, p = 5.37e-05) and the level of major infiltrating immune cell as B cells, CD8+ T cells, CD4+ T cells, macrophages, neutrophils, and dendritic cells." (PMID 35111813, 2021). "Collectively, these results suggest that DNA-damaging treatments cause enhanced KIFC1 expression, leading to KIFC1-dependent centrosome clustering in tumor cells." (PMID 33397932, 2021). "Correlation analysis revealed that KIFC1 overexpression was positively associated with advanced stages, tumor size and recurrence (P < 0.05)." (PMID 31340839, 2019). "Taken together our results indicate that HGSOC overexpresses KIFC1, which is associated with poor overall survival suggesting a causative link between KIFC1 and tumor aggressiveness." (PMID 26992853, 2016). "Targeting KIFC1 could significantly enhance the lethality of chemotherapeutic drugs for tumor cells, whose underlying mechanisms may involve centrosome de-cluster, energy metabolism and endoplasmic reticulum dysfunction." (PMID 37955677, 2023). "These PPI network construction results demonstrated that the gene nodes were closely associated with tumor metabolism, e.g., KIFC1 may contribute to the movement of early endocytic vesicles and regulates cilium formation and tumorigenesis." (PMID 37072703, 2023). "However, our analysis revealed that KIFC1 expression was also strongly associated with tumor inflammation, which is associated with tumor metastasis, invasion, and even immunotherapy." (PMID 37789080, 2023). "In particular, cell cycle genes such as CSNK2A1, MCM8, CDK19, KIFC1 and MCM7, among which KIFC1 was previously found to be a factor for poor prognostic and a therapeutic target associated with tumour proliferation in HCC34,35, even though its immunodulatory function has never been described before." (PMID 33431814, 2021). "Furthermore, we developed a potential patient selection centrosome abnormality biomarker appropriate for analysis of formalin-fixed tumor material that is associated with KIFC1 addiction." (PMID 29535384, 2018). "We speculate that the primary tumor expressed KIFC1 to a high enough level to cause epithelial to mesenchymal transition (EMT) that marks the beginning of the metastatic journey." (PMID 25028599, 2014).
tumor (continued). "Our results provide insights into how tumors acquire the high risk of recurrence and therapeutic resistance via activating centrosome clustering, and reveal that blocking KIFC1 phosphorylation may serve as a promising therapeutic strategy for reducing the risk of tumor metastasis and recurrence." (PMID 33397932, 2021). "By crosslinking microtubules and facilitating bipolar spindle formation, KIFC1 prevents chromosomal missegregation, which is a key factor in tumor survival." (PMID 40471955, 2025). "This research utilizes tumor cohort databases to investigate KIFC1 expression disparities, KIFC1 mRNA was found to be significantly upregulated in CCa tissues compared to adjacent non-tumor tissues." (PMID 40379626, 2025). "KIFC1 is markedly overexpressed in various malignancies, including breast, ovarian, liver, and gastric carcinoma, where it influences tumor development through diverse pathways." (PMID 40379626, 2025). "In a xenograft model, KIFC1 overexpression in UMUC-3 significantly increased tumor volume and weight by day 22 compared with controls, confirming its role in tumor growth in vivo." (PMID 39956902, 2025). "The low KIFC1 expression group had smaller tumor sizes (p = 0.02), while the low KPNA2 group was predominantly at the Tis-T1 stage (p = 0.005)." (PMID 39956902, 2025). "On the other hand, KIFC1 expression was significantly high in neoplastic tissues, and it was detected mainly in the nuclei of tumour cells." (PMID 40857057, 2025). "The expression level of MYCBP was also significantly up-regulated in tumor tissues of HeLashUSP25+KIFC1 OE." (PMID 40379626, 2025). "Tumours with silenced KIFC1 exhibited significantly lower growth rates, weights and volumes than those in the control group." (PMID 40857057, 2025). "We established subcutaneous tumour models to explore the function of KIFC1 in regulating PC tumourigenesis." (PMID 40857057, 2025). "Neoplasm histological grade was significantly different between the high KIFC1 expression group and low-KIFC1 expression group (p = 0.0247)." (PMID 40612867, 2025). "miR-532-3p targets and regulates kinesin family member C1 (KIFC1) a tumor-promoting factor, which regulates HCC cell metastasis and invasion through Gankyrin-dependent activation of Twist." (PMID 38584703, 2024). "In conclusion, KIFC1 was consistently found to be overexpressed in STS and was linked to tumor progression." (PMID 39387242, 2024). "Our data showed that TRIM37 overexpression inhibited inflammatory injury and tumor metastasis in lung tissues, which was reversed by KIFC1 overexpression." (PMID 39349439, 2024). "Results showed that TRIM37 overexpression markedly inhibited tumor growth, which was abolished by KIFC1 overexpression." (PMID 39349439, 2024). "The results revealed significant upregulation of KIFC1 in various tumor types, including BLCA, LUAD, PAAD, STAD, OV, and others, as determined through paired and unpaired comparisons using data from TCGA and GTEx cohorts." (PMID 38112634, 2023). "According to the provided information, immunofluorescence (IF) images demonstrated that the KIFC1 protein exhibited predominant localization in the centrosome of Hela and U251 tumor cell lines." (PMID 38112634, 2023). "In conclusion, these findings indicate the potential utility of KIFC1 as both a tumor marker and a promising target for therapeutic interventions." (PMID 37955677, 2023). "These are consistent with the results of our bioinformatics analysis, which showed a very significant positive correlation between the expression of KIFC1 expression and DNA replication, G2/M checkpoint, and tumor proliferation signaling pathways." (PMID 37789080, 2023). "In conclusion, our work shows the potential utility of KIFC1 as both a tumor marker and a promising target for therapeutic interventions." (PMID 37955677, 2023). "Based on GO and KEGG clustering results, we analyzed the correlation of KIFC1 with tumor-related signaling pathways using the ssGSEA algorithm." (PMID 37789080, 2023).
tumor (continued). "A significant increase of KIFC1 expression was observed in tumor tissues relative to healthy tissues." (PMID 37789080, 2023). "Through bioinformatics and proteomics, we will further investigate the molecular mechanisms underpinning KIFC1’s role in fostering tumor progression." (PMID 37955677, 2023). "High expression of KIFC1 positively correlated with infiltration of tumor cells as well as dysfunction of T cells significantly." (PMID 37789080, 2023). "In contrast, in adjacent tissues, the expression of KIFC1 was significantly increased, while in tumor tissues, the expression of KIFC1 was drastically elevated." (PMID 37955677, 2023). "Coincidentally, KIFC1 was shown to promote the proliferation of tumor cells by regulating AKT, CENPE, ZWINT, and other pathways." (PMID 37789080, 2023). "Through bioinformatics analysis, we found that the high expression of KIFC1 is significantly positively correlated with tumor proliferation, DNA replication, and other signaling pathways." (PMID 37955677, 2023). "In this study, we systematically analyzed KIFC1 expression in tumors and its correlation with tumor prognosis by bioinformatics." (PMID 37789080, 2023). "In tumors with high expression of KIFC1, the marker genes of immune dysfunction in the late stage of the tumor significantly increased." (PMID 37789080, 2023). "As a member of KIFs, KIFC1 plays a pivotal role not only in various cellular events but also in carcinogenesis, malignant progression, and tumor recurrence." (PMID 38112634, 2023). "Our research reveals a significant positive correlation between high KIFC1 expression and various metabolic pathways, which are believed to endow the tumor with stronger immune infiltration and a more complex immune microenvironment." (PMID 37789080, 2023). "The expression of KIFC1 showed a significant positive correlation (Spearman coefficient > 0.7) with tumor proliferation-related pathways (tumor proliferation, G2/M checkpoint, and DNA replication) and tumor inflammation." (PMID 37789080, 2023). "By using the SangerBox “Estimate infiltration” module, we calculated the correlations of the ImmuneScore, the StromalScore, and the ESTIMATEScore with the KIFC1 expression in 32 tumor types on the basis of the TCGA database." (PMID 35327439, 2022). "The corresponding heatmap data show significant and positive correlations between KIFC1 and the top five genes in all of the tumor types in the TCGA database." (PMID 35327439, 2022). "We found that mice bearing KIFC1-WT tumors (3 out of 10) and KIFC1-S26D tumors (4 out of 10) showed recurrence in situ for at least 120 days after surgical removal of the original tumor." (PMID 33397932, 2021). "We found that KIFs are significantly correlated with different grades of tumor, including KIFC1/2C/4A/11/14/15/18A/18B/20A/20B/23." (PMID 34557409, 2021). "KIFC1 mRNA expression was correlated with tumor grade and TNM staging, which was negatively correlated with overall survival and disease-free survival." (PMID 35111813, 2021). "Across the 393 patient samples assessed in the TCGA-PRAD provisional dataset (accessed November 20, 2019) KIFC1 mRNA expression was significantly increased with higher tumor stage (P < 0.0001)." (PMID 33760984, 2021). "The overexpression of KIFC1 has been reported to lead to the formation of monopolar spindles in tumor cells." (PMID 35111813, 2021).
tumor (continued). "It was also shown that higher KIFC1 levels are present in primary tumor samples compared to matched solid (normal) tissue samples." (PMID 33760984, 2021). "In TCGA-PRAD provisional dataset primary tumor KIFC1 mRNA expression was higher than matched solid tissue." (PMID 33760984, 2021). "Specifically, the KIFC1 mRNA expression level showed intense correlation with tumor immunity, such as tumor-infiltrating immune cells and immune scores as well as multiple immune-related genes." (PMID 35111813, 2021). "It revealed that the transcription level of KIFC1 was markedly higher compared with normal liver tissue in different subgroups according to age, tumor stage, and grade (p < 0.001)." (PMID 35111813, 2021). "Although CW069 and VE-822 are not specific inhibitors of KIFC1 or KIFC1-S26 phosphorylation, they both prevent tumor recurrence through KIFC1 inhibition." (PMID 33397932, 2021). "In this study, KIFC1 mRNA expression was found to be higher in metastatic PCa lesions compared to the primary tumor." (PMID 33760984, 2021). "This study aims to explore the diagnostic value of KIFC1 gene in LIHC and its influence on tumor immune invasion." (PMID 35111813, 2021). "Here, the authors show that in response to DNA damage, ATM/ATR stabilize the centrosome clustering regulator KIFC1 leading to increased clustering efficiency and tumour recurrence." (PMID 33397932, 2021). "High KIFC1 expression was correlated with high Gleason score, high tumor stage, metastatic lesions, lower recurrence-free survival, and higher ploidy levels." (PMID 33760984, 2021). "Similar trends were shown across the 116 patient samples in the DKFZ dataset where KIFC1 mRNA expression was also significantly increased with higher tumor stage (P < 0.0001)." (PMID 33760984, 2021). "We stained the tumor tissue microarrays using anti-KIFC1 antibody and classified the specimens into low, medium, and high KIFC1 expression groups according to the immunohistochemical (IHC) scores." (PMID 33397932, 2021). "The results showed that the xenograft tumors with KIFC1-S26A were more sensitive to etoposide than those of KIFC1-WT and KIFC1-S26D (observed by a reduction of tumor volume and weight)." (PMID 33397932, 2021). "KIFC1 mRNA expression increased as tumor stage increased in multiple datasets indicating higher stage tumors likely have higher levels of KIFC1 mediated centrosome clustering." (PMID 33760984, 2021). "The correlation of KIFC1 with tumor immune cell infiltration, immune checkpoints, immune-related genes, and responses to ICB and drugs was detected." (PMID 35111813, 2021). "Next, we investigated the in vivo activity of KIFC1-S26 phosphorylation on drug resistance using the murine tumor xenograft model generated with the KIFC1-WT, KIFC1-S26A, or KIFC1-S26D rescued MDA-MB-231 cells." (PMID 33397932, 2021). "KIFC1 is a c-type terminal kinesin that plays an indispensable role in the centrosomal aggregation of tumor cells." (PMID 32391047, 2020). "The results from our HCC cell assays and mouse model demonstrated that KIFC1 overexpression promoted tumor proliferation and metastasis." (PMID 31340839, 2019). "For HCC orthotopic models, the tumor nodule number spread into the liver of the KIFC1 ectopic expression group was higher than that in the vector group." (PMID 31340839, 2019). "The tumor volume in the KIFC1 knockdown group was significantly less than that in the control group." (PMID 31340839, 2019). "We therefore sought to augment the effect of KIFC1 depletion by combining it with a clinically relevant therapy capable of further induction of centrosome amplification in tumor cells." (PMID 29535384, 2018). "We subsequently examined the consequence of KIFC1 silencing on the tumor growth of centrosome-amplified cell line xenografts with MDA-MB-231 and HCC1954 cells in vivo." (PMID 29535384, 2018). "In our previous study, we emphasized the role of KIFC1 in tumor progression of EOC at the gene expression level." (PMID 26992853, 2016).